GKN1 (gastrokine 1)
Description:
Has mitogenic activity and may be involved in maintaining the integrity of the gastric mucosal epithelium.
Synonyms: AMP18; CA11; BRICD1; FOV; foveolin
Tractability: Antibody: UniProt places it where antibodies can reach, with high confidence; its Gene Ontology location is reachable by antibodies, with high confidence; UniProt predicts a signal peptide or a membrane-spanning region.
Gene: Protein-coding gene on chromosome 2 (68,974,573 to 68,980,980, forward strand). Ensembl gene ENSG00000169605.
Subcellular location: Secreted; Cytoplasmic granule; Golgi apparatus
Gene Ontology:
Molecular function: protein binding; growth factor activity
Biological process: digestion; regulation of cell population proliferation; signal transduction
Cellular component: extracellular region; Golgi apparatus; cytoplasm; endomembrane system; secretory granule
Genetic constraint (gnomAD): Loss-of-function variants: 4 observed, 4.59 expected, observed/expected ratio (o/e) 0.87, 90% interval 0.42 to 1.75. That is too few expected variants to judge how well the gene tolerates losing a copy. Missense variants: 62 observed, 68.12 expected, observed/expected ratio (o/e) 0.91, 90% interval 0.74 to 1.12. Synonymous variants: 26 observed, 21.52 expected, observed/expected ratio (o/e) 1.21, 90% interval 0.88 to 1.67.
Homologues: Orthologues: chimpanzee GKN1 (98% identical), macaque GKN1 (88% identical), pig GKN1 (75% identical), dog GKN1 (73% identical), rabbit GKN1 (70% identical), guinea pig GKN1 (68% identical), mouse Gkn1 (64% identical), rat Gkn1 (62% identical). Paralogues in human: GKN2 (25% identical), BRICD5 (17% identical).
Diseases named in the same sentence as GKN1 in open-access papers:
GKN1 is named in the same sentence as 37 diseases in open-access papers, as found by Europe PMC text mining. Sharing a sentence is not in itself a finding about the gene and the disease. The quoted sentences say what the papers report.
gastric cancer (41 papers, 2006 to 2025). A primary or metastatic malignant neoplasm involving the stomach. "The mechanisms underlying GKN1's role in gastric cancer cell invasion and metastasis remain incompletely elucidated." (PMID 39524138, 2024). "It is possible that, since GKN1 is expressed in differentiated gastric epithelial cells, the loss of GKN1 in gastric cancer reflects the loss of epithelial cell differentiation." (PMID 33947892, 2021). "Further studies are strongly recommended to identify the molecular mechanism underlying low serum GKN1 protein concentrations in gastric cancer patients." (PMID 31376239, 2019). "The application of serum GKN1 concentration as a diagnostic marker for gastric cancer worldwide requires a multinational study." (PMID 31376239, 2019). "We found previously that loss of GKN1 expression occurs frequently in gastric cancers and that GKN1 inhibits cell proliferation and induces apoptosis." (PMID 25344918, 2014). "Because of the high sensitivity and specificity of GKN1, the levels of GKN1 in serum could be regarded as informative diagnostic and gastric cancer‐specific diagnostic biomarker." (PMID 39524138, 2024). "According to other studies, GKN1 is highly expressed in normal mucosal tissues but is lost in gastric cancer cells, suggesting that that GKN1 expression may be a diagnostic marker for gastric cancer." (PMID 39524138, 2024). "Another study indicated that the downregulation of serum exosomal Gastrokine 1 (GKN1) protein may be a valid diagnostic biomarker in gastric cancer patients." (PMID 36119470, 2022). "Similarly, a decrease in exosomal gastrokine-1 level has been shown to be associated with gastric cancer." (PMID 35884376, 2022). "The loss of GKN1 expression is associated with gastric cancer leading to the suggestion that GKN1 may be a tumor suppressor gene." (PMID 33947892, 2021). "Here, serum GKN1 concentrations were examined in patients with HCC, CRC, NSCLC, BRC, PAC, OVC, and PRC to further confirm the potential diagnostic utility of serum GKN1 concentrations in differentiating healthy individuals from patients with non‐gastric cancers." (PMID 31376239, 2019). "The objective of this study was to determine whether serum gastrokine 1 (GKN1) protein is a gastric cancer‐specific diagnostic biomarker." (PMID 31376239, 2019). "The serum GKN1 protein could serve as an excellent diagnostic biomarker for early detection of gastric cancer." (PMID 31376239, 2019). "We previously showed that GKN1 down-regulation is one of the leading causes of gastric cancer (GC) development." (PMID 28129645, 2017). "The results of our study present for the first time that GKN1 may play a role in telomere maintenance by inhibiting c-myc-induced telomerase activation in gastric epithelial cells and that loss of GKN1 expression in gastric cancer cells may activate telomerase." (PMID 25344918, 2014). "The expression of GKN1 is downregulated in gastric tumor tissues and derived cell lines, while its overexpression in gastric cancer cell lines induces apoptosis." (PMID 39524138, 2024). "Our findings demonstrate that exosomes isolated from gastric cancer cell lines contain multiple functional factors, including GKN1, and that upregulation of exosomal GKN1 can inhibit the migration and invasion of gastric cancer cells." (PMID 39524138, 2024). "The study utilized gastric cancer cell lines and a xenograft mouse model to investigate the functional significance of exosomal GKN1." (PMID 39524138, 2024). "The primary objective of this research study was to identify a potential therapeutic target for further investigation of exosomal GKN1 in gastric cancer." (PMID 39524138, 2024).
gastric cancer (continued). "Gastrokine 1 transferred by gastric cancer exosomes inhibits growth and invasion of gastric cancer cells both in vitro and in vivo via regulating PI3K/AKT/mTOR signaling pathway." (PMID 39524138, 2024). "The findings suggest that exosomal GKN1 exerts inhibitory effects on gastric cancer cell growth and invasion through the regulation of the PI3K/AKT/mTOR signaling cascade, both in experimental cell cultures and animal models." (PMID 39524138, 2024). "As a result of our research, we obtained mechanistic insights into GKN1's role in gastric cancer progression and developed a valuable marker to help diagnose and treat gastric cancer." (PMID 39524138, 2024). "In gastric cancer, gastrokine 1 (GKN1) is a potential theragnostic marker while the related mechanisms remain elusive." (PMID 39524138, 2024). "This study investigated the effects of gastric cancer‐derived exosomal GKN1 on AGS and N87‐C cells, as well as a mouse model." (PMID 39524138, 2024). "GKN1 and GKN2 are mainly expressed in the stomach, and decreased GKN1 expression has been linked to gastric cancer." (PMID 39300663, 2024). "In H. pylori infection, GKN1 expression is downregulated depending on disease severity, so it was thought that GKN1 was completely abolished in gastric cancer cases." (PMID 36317116, 2022). "On the other hand, some authors propose that GKN1 possibly suppresses the CagA-induced effects on epithelial cells avoiding the gastric cancer progression." (PMID 36317116, 2022). "The role of GKN1 in senescence via p16 and p21 upregulation has already been shown in the context of gastric cancer." (PMID 35082384, 2022). "It has been previously shown in vitro that gastric cancer cells stably expressing GKN1 or being exposed to GKN1 protein, resulted in cellular retention in G1 cell cycle phase." (PMID 35082384, 2022). "The serum GKN1 protein concentration clearly distinguished patients with gastric cancer from healthy individuals with an AUC value of 0.9954 and a Youden index of 0.8740." (PMID 31376239, 2019). "At the optimum cutoff (4.94 ng/μL) of serum GKN1 protein, the sensitivity and specificity were 91.2% and 96.0%, respectively, for gastric cancer." (PMID 31376239, 2019). "The serum GKN1 protein levels were lower in the gastric cancer patients compared to healthy individuals." (PMID 31376239, 2019). "At a serum GKN1 cutoff value of 4.94 ng/μL the sensitivity, specificity, Youden index, diagnostic accuracy and DOR for gastric cancer diagnosis were 91.2%, 96%, 0.8740, 0.9257, and 248.73, respectively." (PMID 31376239, 2019). "The serum GKN1 protein concentrations were significantly lower in the gastric cancer patients (median: 3.48 ng/μL, IQR: 2.90‐4.11 ng/μL) compared with healthy individuals (median: 6.34 ng/μL, IQR: 5.66‐7.54 ng/μL; P < .0001)." (PMID 31376239, 2019). "Analysis of preoperative and periodic postoperative serum GKN1 protein concentrations can be used to predict the response to treatment and monitor the recurrence of gastric cancer." (PMID 31376239, 2019). "The serum GKN1 concentration of 4.94 ng/μL was considered as the optimal cutoff value for gastric cancer diagnosis." (PMID 31376239, 2019). "In conclusion, serum concentrations of GKN1 clearly distinguished patients with gastric cancer from healthy controls and those with non‐gastric cancers." (PMID 31376239, 2019). "When we selected 4.94 ng/μL as the cutoff value for serum GKN1 protein in both gastric cancers, the sensitivity and specificity were 79.3% and 96.0% for EGC, respectively, and 95.8% and 96.0% for AGC, respectively." (PMID 31376239, 2019). "Taken together, these results suggest that serum GKN1 protein represents a biomarker for gastric cancer diagnosis with exquisite sensitivity and specificity." (PMID 31376239, 2019). "Given its high sensitivity and specificity, serum GKN1 protein can be used as a serological marker for the diagnosis of gastric cancer." (PMID 31376239, 2019).
gastric cancer (continued). "Thus, we conclude that serum GKN1 protein could be a gastric cancer‐specific diagnostic biomarker." (PMID 31376239, 2019). "The serum levels of GKN1 protein have clearly distinguished the gastric cancer patients from healthy individuals." (PMID 31376239, 2019). "GKN1 is overexpressed in the stomach and is downregulated in gastric cancer tissue as compared to normal gastric mucosa." (PMID 28974199, 2017). "Inactivation of GKN1 downregulates expression of E-cadherin and increases expression of βcatenin in gastric cancers." (PMID 29348895, 2017). "GKN1 is down-regulated in gastric tumor tissues and derived cell lines and its over-expression in gastric cancer cells induces apoptosis, suggesting a possible role for the protein as a tumor suppressor." (PMID 28129645, 2017). "Aberrant SOX9 expression contributes to the development of gastric cancer by inactivation of GKN1 as an early event." (PMID 29348895, 2017). "Gastrokine 1 (GKN1) was reported to inhibit hTERT expression in gastric cancer cells by binding directly to c-Myc and downregulating its expression, leading to lower hTERT promoter activity." (PMID 27548225, 2016). "Previously, we demonstrated that GKN1 inactivation is frequently detected in gastric cancers and that GKN1 inhibits cell proliferation while inducing senescence and apoptosis." (PMID 26314965, 2015). "We and others have reported previously that GKN1 has a tumor suppressor function through inhibition of cell proliferation and induction of apoptosis in gastric cancer cells." (PMID 25344918, 2014). "Here, we provide molecular evidence for the involvement of GKN1 in the regulation of telomere length and telomerase activity through direct binding to c-myc, resulting in senescence and apoptosis in gastric cancer cells." (PMID 25344918, 2014). "In contrast to that of gastric cancer tissues, telomere length in the gastric mucosal tissues expressing GKN1 was longer." (PMID 25344918, 2014). "Overall, we showed that GKN1 promotes senescence and apoptosis by regulating the length of telomeres in gastric cancers." (PMID 25344918, 2014). "Gastrokine-1, another member of the gastrokine family, has been demonstrated to introduce apoptosis in gastric cancer cells mainly through the Fas/FasL pathway." (PMID 25270871, 2014). "The data of the present study also suggests a decreased GKN-1 can be found in gastric cancer tissues." (PMID 24404153, 2014). "In this study, we focused on the effect of GKN1 on telomere maintenance and senescence in gastric cancer tissues and cell lines." (PMID 25344918, 2014). "Telomere length in 35 gastric cancers was shortened significantly compared with the corresponding gastric mucosae, whereas GKN1 expression was inversely correlated with telomere length and c-myc and hTERT mRNA expression." (PMID 25344918, 2014). "Recently, it has been reported that GKN1 induces senescence by activating p16/Rb pathway in gastric cancer cells." (PMID 25344918, 2014). "GKN1 and GKN2 have been identified based on their frequent loss of expression in neoplastic gastric carcinoma epithelial cells, compared to normal gastric tissue." (PMID 24460791, 2014). "We next measured GKN1 or GKN2 mRNA levels in various gastric carcinoma cells lines and in primary normal gastric tissue by qRT-PCR." (PMID 24460791, 2014). "We found that GKN1 mRNA was weakly expressed in gastric cancer MKN 28 cells, and was absence in AGS, N87, MKN45, SNU16, SNU1, and KATO cells." (PMID 22621392, 2012). "The primary aim of this study was to identify and characterize GKN1 as a potential tumor suppressor in gastric cancer." (PMID 22621392, 2012). "GKN1 protein was weakly expressed in 2 gastric cancer tissues, and absence in the remaining 37 tissues." (PMID 22621392, 2012). "The present study investigated differential expression of GKN1 in normal, precancerous, and cancerous gastric tissues, and explored the biological functions of GKN1 protein in gastric cancer cells." (PMID 22621392, 2012).
gastric cancer (continued). "In 39 gastric cancer tissues, GKN1 mRNA was only weakly expressed in 3 tissues, and absence in the remaining 36 tissues." (PMID 22621392, 2012). "We found that restoration of GKN1 expression suppressed tumor cell viability and induced them to undergo apoptosis and enhanced effects of 5-FU on gastric cancer cells." (PMID 22621392, 2012). "So far, we had demonstrated that GKN1 expression was able to induce apoptosis in gastric cancer cells." (PMID 22621392, 2012). "In the current study, we investigated expression of GKN1 mRNA and protein in tissue specimens from normal gastric mucosa, atrophic gastritis, intestinal metaplasia, dysplastic lesions, and gastric cancer." (PMID 22621392, 2012). "Our current study using the gene transfection technique demonstrated that induction of GKN1 expression induced apoptosis of gastric cancer AGS cells." (PMID 22621392, 2012). "RT-PCR, Western blot, and immunohistochemistry were performed to detect GKN1 expression in normal, precancerous, cancerous gastric tissues and seven gastric cancer cell lines." (PMID 22621392, 2012). "Restoration of GKN1 expression induced gastric cancer cells to undergo apoptosis, and enhanced sensitivity to 5-FU-induced apoptosis." (PMID 22621392, 2012). "We then investigated the possible biological functions of GKN1 in gastric cancer cells by assessing the resulting phenotypic changes in GKN1 transfected cells." (PMID 22621392, 2012). "Down regulation of this protein in gastric carcinoma was postulated to be responsible for several diseases affecting the stomach, but only the potential role of gastrokine-1 in mucosal protection was proposed." (PMID 19057650, 2008). "Tripartite motif-containing 3 (TRIM3) and gastrokine 1 (GKN1) were found to be downregulated in plasma exosomes in gastric cancer (GC) compared with those in healthy controls, so these factors are thought to be novel biomarkers for GC diagnosis and therapeutic targets." (PMID 38814362, 2024). "Previous studies have shown that GKN1 expression is reduced in gastric cancer cells and tissues." (PMID 39524138, 2024). "The expression of GKN1 protein exhibits a progressive downregulation pattern, moving from normal gastric mucosa to atrophic gastritis, intestinal metaplasia, dysplasia, and ultimately to gastric cancer." (PMID 38617533, 2024). "In addition, in the development of gastric cancer in humans and mice, the highly coordinated deletion of GKN1/GKN2 genes and the abnormal expression (deletion) of GKN are closely related to the occurrence of precancerous inflammation and gastric cancer." (PMID 38250608, 2024). "Additionally, exosomes containing GKN1 reduce tumor volume and weight and inhibit gastric cancer by downregulating HRas/Raf/MEK/ERK signals." (PMID 39524138, 2024). "Furthermore, the study explored the impact of GKN1 on gastric cancer xenograft tumor mice, specifically focusing on inflammation, cell proliferation, and PI3K/Akt/mTOR signaling pathways." (PMID 39524138, 2024). "Moreover, GKN1 in serum of patients with advanced gastric cancer (AGC) were lower than those of patients with early gastric cancer (EGC)." (PMID 35066729, 2023). "For example, a lower expression of genes that may play an important role in suppressing gastric cancer (GKN1, LIPF, ANXA10, MUC6, PSCA, and SNHG5) was found." (PMID 35625760, 2022). "Although we did not observe spontaneous gastric cancers in GKN1−/− mice we cannot rule out the possibility that loss of GKN1 predisposes to gastric cancer in the context of other additional inducers such as inflammation or infection." (PMID 33947892, 2021). "A study of gastric cancer suggests that miR-1245b-3p can directly target the 3′UTR of GKN1." (PMID 34922523, 2021). "Finally, we report that the specificity and sensitivity of serum GKN1 concentration for the detection of gastric cancer were 91.2% and 96%, respectively." (PMID 31376239, 2019).